STAT3 (signal transducer and activator of transcription 3)
Diseases named in the same sentence as STAT3 in open-access papers (continued):
Sharing a sentence is not in itself a finding about the gene and the disease.
tumor (continued). "Then, p-STAT3 enters into the nucleus and promotes tumor cell proliferation, drug resistance, or suppresses tumor cell apoptosis." (PMID 28797050, 2017). "In Mx1-Cre;Gankyrinf/f mice, STAT3 activity was decreased in inflammatory cells whilst ERK activity was decreased in tumor cells as well as inflammatory cells." (PMID 28160571, 2017). "In this study, we also found reduction of STAT3 phosphorylation in tumor tissue, in which angiogenesis was inhibited by fucoidan." (PMID 28764703, 2017). "CuB also inhibited IL-10-induced STAT3 phosphorylation, synergistically increasing the anti-tumor activity of Adriamycin in vitro." (PMID 27418139, 2017). "Our efforts are focused on understanding the correlation between STAT3 PTMs, as well as STAT3 protein interactors and gene expression at different clinical tumor stages." (PMID 28489571, 2017). "Using a proteomics approach, we identified elevated STAT3 expression in ICC tumor tissues compared with para-tumor specimens." (PMID 28032598, 2017). "A critical role for STAT3 in promoting proliferation, metastasis and immune evasion of tumor cells has been shown in various pathophysiologic conditions." (PMID 28912452, 2017). "STAT3 is a critical element in inflammation-related tumorigenesis as it promotes the proliferation, survival, invasion, angiogenesis, and metastasis of tumor cells." (PMID 29194365, 2017). "We also examined the importance of STAT1 in tumours that retain high (MT/ShcA+/+; MT/Shc313F/313F) versus low (MT/Shc2F/2F) STAT3 signalling." (PMID 28276425, 2017). "There are many microRNAs which reduce STAT3 expression by targeting STAT3 mRNA and impair tumor vascular formation." (PMID 28978186, 2017). "Mechanistic studies have indicated that sunitinib can crosstalk with this pathway by inhibiting STAT3 in RCC tumor cells." (PMID 28178674, 2017). "This is in agreement with our previous study showing that REG3A accelerated tumor growth via STAT3 signaling, and with our present findings indicating that Reg3g promoted tumor growth by suppressing immune responses." (PMID 28880262, 2017). "We previously found that STAT3 signaling in tumor cells can potentially decrease leukocyte migration in vitro." (PMID 28008146, 2017). "Studies on mouse cancer models also reveal that Stat3 is a negative regulator for tumor progression in Apc mutant mice and in K-Ras mice." (PMID 29126425, 2017). "In vitro, Reg3g upregulated EGFR in DCs, activated heme oxygenase-1 (Hmox1) involved JAK2/STAT3 signaling, raised levels of Th2 cytokines in and suppressed maturation of DCs, and enhanced tumor cell proliferation." (PMID 28880262, 2017). "Inhibition of the STAT3 signaling is a potential therapeutic strategy for tumor and other angiogenesis related diseases." (PMID 28978186, 2017). "STAT3 is known as a crucial regulator of anti-apoptotic genes, and plays an important role in tumor growth, survival, and angiogenesis." (PMID 28497028, 2017). "STAT3 is known to play an important role in tumor progression of several high-malignant cancer entities." (PMID 28903416, 2017). "We also stained the tissue for human arginase-1 that is transcriptionally upregulated with STAT3, and we found dramatic reduction of this immunosuppressive enzyme in the STAT3 suppressed tumor." (PMID 28008146, 2017). "STAT3 phosphorylation of tumor tissue samples from these mice was also decreased by Raloxifene, suggesting inhibition in STAT3 phosphorylation resulting in the suppression of tumor growth in mice." (PMID 28430601, 2017). "Five-year DFS rates was 77.3% for patients with STAT3-positive tumors versus only 42.7% for patients with STAT3-negative tumors, even though patients with STAT3 positive tumors had a more advanced tumor stage in our cohort." (PMID 28903353, 2017).
tumor (continued). "With the aim of elucidating the relationship between Stat3 expression and tumor vessels abnormalities in the PCNSL, we evaluated Stat3 and pStat3 expression by Real-time PCR and by immunohistochemistry in biopsy sections from PCNSL patients." (PMID 28415725, 2017). "The need of a larger candidate pool applies to almost every therapy strategy of tumor, which is also true for targeting STAT3." (PMID 28588262, 2017). "STAT3 also promotes tumor immune escape by governing multiple immunosuppressive mechanisms including macrophage polarization to the M2 phenotype, inhibition of DC development, and accumulation of immunosuppressive cells such as Tregs, Th17 cells, and MDSCs26." (PMID 28338101, 2017). "The level of acetyl-STAT3 (K685) was reduced in tumor samples treated with SH-I-14 compared to tumor samples treated with DMSO control." (PMID 29137356, 2017). "Taken together, G6PD promotes tumor cell proliferation possibly through ROS-stimulated persistent activation of p-STAT3 signaling and up-regulated CyclinD1 expression in RCC." (PMID 29312589, 2017). "CA10 induced ROS, activated the ER stress pathway and inhibited STAT3 phosphorylation and gastric xenografts tumor growth in mice." (PMID 29254150, 2017). "Studies have shown that persistent activation of STAT3 is an important reason of tumor proliferation and metastasis." (PMID 29070894, 2017). "As a result, persistent Stat3 target gene activation can promote tumor development and sustain tumorigenesis." (PMID 28061445, 2017). "These IL-22-producing cells can promote tumor growth and metastasis by activating STAT3 and inducing the expression of antiapoptotic factors such as BCL-XL." (PMID 28852270, 2017). "It's reported that parthenolide can inhibit STAT3 activity and therefore suppress the development of tumor." (PMID 28423582, 2017). "One important mechanism of IL-6 procancerous action is activation of epithelial STAT3, a critical component of tumor-stimulating signaling in colon and other organs." (PMID 28350804, 2017). "STAT3 has a global role in the adaptation of tumour cells to a hypoxic microenvironment, and constitutively active STAT3 leads to increased VEGF expression and increased vasculogenesis." (PMID 28978141, 2017). "The autocrine IL-8 loop activates AKT, MAPK and STAT3 signaling pathways in tumor cells, which in turn induce the upregulation of transcription factors such as Snail, Slug, and Twist." (PMID 28947965, 2017). "Downstream target gene analysis indicated that both canonical NF-κB and STAT3 pathways were attenuated in DCs cultured in tumour serum." (PMID 28350008, 2017). "We next examined the relationship between the STAT3 expression in tumor tissues and various clinicopathological characteristics of 159 ICC patients using TMA analysis." (PMID 28032598, 2017). "Studies also have shown that TC-PTP can suppress tumor growth by down-regulating STAT3 signaling in several types of cancers including breast cancer and colon cancer." (PMID 29207596, 2017). "Our data suggests that elevated STAT3 immunosuppressive signals enable persistent STAT1 activation by limiting its anti-tumour responses and thereby potentiating STAT1-driven, PD-L1-dependent induction of T-cell tolerance." (PMID 28276425, 2017). "In contrast, STAT3 and MAPK activation results in M2 macrophage polarization, which is associated with immune suppression and tumor progression." (PMID 29245934, 2017). "STAT3 was overexpressed in tumor samples compared to counterpart normal lung tissues and was inversely associated with prognosis of the patients." (PMID 27835873, 2017). "STAT3 has very recently been found to promote tumor progression by promoting desmoplastic reactions and tumor invasion." (PMID 29066712, 2017). "The novel small molecule inhibitor LY5, inhibited STAT3 phosphorylation and tumor cell viability in vitro and exhibited favorable PK properties in both mice and dogs including good oral bioavailability." (PMID 28750090, 2017).
tumor (continued). "STAT3 silencing in tumor models induces tumor cell death, leading to tumor regression, and inhibits CRC metastasis." (PMID 28503147, 2017). "This was unexpected, since in various other human malignancies STAT3 activation promotes tumor growth and resistance to chemotherapy." (PMID 28895886, 2017). "Our study suggests that inhibition of STAT3 signalling, specifically in the tumour epithelium, robustly engages immune surveillance." (PMID 28276425, 2017). "These cytokines activate the STAT3/NF-kB pathways in tumor and stromal cells generating positive feedback loops that contribute to CSC self-renewal." (PMID 28938604, 2017). "Here, the authors show using a mouse model the tumor immunotherapeutic efficacy of nanovaccines based on intertwining DNA-RNA nanocapsules loaded with DNA CpG, Stat3-silencing short hairpin RNA and tumor-specific peptide neoantigens." (PMID 29133898, 2017). "We use this system to analyze the immunological consequences of STAT3 signaling disruption on the human tumor microenvironment (TME)." (PMID 28008146, 2017). "STAT3 inhibition stunts tumour growth by inducing cell apoptosis in many types of malignant tumours." (PMID 28423603, 2017). "Inhibitory molecules, which down-regulate Stat3 phosphorylation and induce apoptosis in tumor cells have been developed." (PMID 28415725, 2017). "We next analyzed the activation status of STAT3, a transcription factor important for both tumor growth and maintenance of stemness in embryonic stem cells." (PMID 28337983, 2017). "Constitutive activation of STAT3 signaling has been observed in aggressive forms of cancer and is crucial in regulating tumor cell proliferation and survival in diverse cancer types." (PMID 28222747, 2017). "As an important member of the signal transducers and activators of transcription (STAT) protein family, STAT3 expression and signalling have been identified in tumours of the breast, ovary, pancreas, prostate, and melanoma." (PMID 28661466, 2017). "On the other hand, pS727-STAT3 and the glutathionylated-STAT3 forms were highly expressed in the most malignant tumor (Gleason 8 and 9) together with an increase in the APE1/Ref-1 and PDIA3/ERp57 levels which are known to be present under oxidative stress." (PMID 28489571, 2017). "The release of IL-6 is biologically related to an induction of tumor cell proliferation and inhibition of cellular apoptosis through the involvement of Janus kinases (JAKs) and signal transducer and activator of transcription 3 (STAT3)." (PMID 28264501, 2017). "Next, we measure the levels of STAT3 phosphorylation in tumor samples and found that the in vivo treatment of luteolin significantly downregulated STAT3 phosphorylation and Mcl-1, Bcl-xl, Survivin expression at both protein and transcription levels." (PMID 28182003, 2017). "On the contrary, blockade of Stat3 function is sufficient to inhibit tumor cell growth and induce apoptosis." (PMID 28360411, 2017). "Together, these results suggested that Btk inhibition exerts anti-tumor immunomodulatory effects through the regulation of NF-κB, STAT3, and AP-1 activation in macrophages." (PMID 28424405, 2017). "BM cells can also promote the expansion of myeloid-derived suppressor cells (MDSCs) within the tumor microenvironment by inducing secretion of VEGF from MCs that in turn can activate JAK2/STAT3 signaling in myeloid progenitor cells." (PMID 28626727, 2017). "With a VEGF inducer and inhibitor, however, we showed that nobiletin inhibited tumor angiogenesis by regulating Src/FAK/STAT3 through PXN." (PMID 28468300, 2017). "Our findings are consistent with previous data, showing the capability of DHA to inhibit STAT3 in other tumor cell models." (PMID 28435516, 2017). "For instance, Y. Fujiwara and colleagues reported that corosolic acid suppresses the M2 polarization of macrophages and tumor cell proliferation by inhibiting both STAT3 and NF-κB activation." (PMID 28045028, 2017).
tumor (continued). "Using STAT3 siRNA method, we silenced STAT3 signaling in Cal27 tumor cells and compared them with Cal27 transduced with control lentivirus." (PMID 28008146, 2017). "For example, in human tumor cell lines, a proteomic study found a significant link between PI3K and STAT3 in human cancer causing enhanced phosphorylation, with its effects reversible with PI3K inhibitors." (PMID 29049295, 2017). "In H460 lung cancer cells, curcumin was able to reduce the tumor spheres and repress tumor growth in xenograft mouse model via inhibiting the JAK2/STAT3 signaling pathway." (PMID 28156178, 2017). "In these mentioned studies, STAT3 has been described as an oncogene, however, there are some other publications in which STAT3 has been shown to be a tumor suppressor." (PMID 28709401, 2017). "EGCG did not alter cisplatin-induced apoptosis of human-derived cancer cells or cisplatin antitumor efficacy in a xenograft tumor model in mice because of its inability to rescue the downregulation of STAT3 in these cells." (PMID 28703809, 2017). "For instance, tumor and T-regulatory cell-derived IL-10 can skew macrophages toward an anti-inflammatory phenotype characterized by activation of STAT3 and increased expression of CD163, CCL18, and SOCS3." (PMID 28881599, 2017). "We found that the levels of tumor-specific IgG antibodies from mice immunized with the STAT3-blocked HCC vaccine were significantly increased." (PMID 29115974, 2017). "The signal transducer and activator of transcription-3 (STAT-3) can contribute to tumor progression by suppressing anti-tumor immunity and apoptosis, and inducing cell proliferation." (PMID 28915576, 2017). "On this last point, we evaluated the capability of DHA to counteract STAT3 activation triggered by tumor cell-released factors in both PBMCs and DCs." (PMID 28435516, 2017). "We have significantly observed higher levels of TNF-α in BC, which act in tumor cell survival through activation of the Factor nuclear kappa B (NF-κB) and Signal transducer and activator of transcription 3 (STAT3) signaling pathways." (PMID 29186783, 2017). "Building on these results, we found for the first time a link between induced STAT3 signaling and hepatocyte-specific SMAD7 deficiency in DEN mice and human HCC, thus unraveling a new tumor-suppressive mechanism for SMAD7 in HCC." (PMID 28134936, 2017). "As is known, inappropriate activation of STAT3 not only promotes the survival of the tumor cells, but also facilitates tumor migration, invasion and metastasis." (PMID 27275540, 2017). "Phosphorylation of Stat5 and Stat3, which has been reported in various tumor cells following EPO-mediated Jak2 activation was next examined." (PMID 28415825, 2017). "Immunohistochemistry of tumor tissues revealed that tumors administrated with IL-22 had higher p-STAT3, c-Myc, and HK2 expression than that in control group." (PMID 28445985, 2017). "In clinic, IL-6-mediated STAT3 abnormal activation predicts tumor progression and poor prognosis in breast, lung, and hematopoietic tumors with gp130 constitutive activation or elevated IL-6 levels." (PMID 27861147, 2017). "A number of natural products have been reported to inhibit STAT3 activity and induce apoptosis in different tumor cell lines." (PMID 28570563, 2017). "STAT3 expression correlated with several clinicopathological features, including tumor size, pathological satellite, vascular invasion, undifferentiated-type histology, lymph node metastasis and TNM stage in two independent cohorts of ICC patients." (PMID 28032598, 2017). "The mechanism involved inhibits phosphorylation of STAT3, which boosts the capacity of macrophages to promote cytotoxic response and presentation of tumor antigens." (PMID 28970834, 2017). "The results showed that serum from mice immunized with the STAT3-blocked HCC vaccine significantly inhibited tumor growth compared with serum from the controls." (PMID 29115974, 2017).
tumor (continued). "In the present study, we found that chemotherapy initiated a STAT3 pathway to spur tumor cells resistant to drug stimuli." (PMID 29072615, 2017). "In vivo assay revealed that SC-43 exhibited xenograft tumor growth inhibition, p-STAT3 reduction and SHP-1 activity elevation." (PMID 29029413, 2017). "After Real-time PCR a significant difference in Stat3 expression between tumor and control brain tissues was observed." (PMID 28415725, 2017). "In this review, we will focus on the roles of STAT3 in mediating the expression of angiogenesis-related genes and discuss the molecular mechanisms behind STAT3-regulated tumor angiogenesis." (PMID 28978186, 2017). "Signal transducer and activator of transcription 3 (STAT3) is a marker for tumor angiogenesis which interacts with Src." (PMID 28468300, 2017). "We found that the levels of STAT3 consistently correlated with CCT2 in most SCLC patient tumor tissues." (PMID 29299146, 2017). "To notice, STAT3 inhibitors on tumor cells, used in combinatorial therapy with immunogenic chemotherapeutics such as anthracyclines, improve the outcome of immunogenic chemotherapy by stimulating the type-1 interferon production by cancer cells." (PMID 28435516, 2017). "Our data demonstrated that sorcin can induce tumor growth and metastasis via STAT3 signaling, leading to development of therapeutic treatments for GC." (PMID 29262638, 2017). "We tested the effect on 6-OAP on STAT3 in vivo by Western blot analysis of lysates of tumor samples isolated from the mice, and found that treatment with 10 mg/kg 6-OAP drastically inhibited pSTAT3 in tumor samples." (PMID 27835873, 2017). "Persistently active Stat3 has been found in various tumor types and tissues including leukemias, cervical, colorectal, and pancreatic cancer, which contributes to tumor initiation, progression, invasion, migration, and formation of metastases." (PMID 32961646, 2017). "Alternol is considered a promising anti‐tumour treatment for some patients and is also a promising STAT3 inhibitor candidate for the development of anti‐tumour drugs that target OS." (PMID 27624867, 2017). "In NSCLC tumor cells resistant to the EGFR TKI gefitinib the expression of CXCR4 maintains stemness through JAK/STAT3 downstream signaling." (PMID 28402937, 2017). "Firstly, inhibiting STAT3 activation in cancer cells hampered tumor cells survival and proliferation." (PMID 28747781, 2017). "To gain further insights into the effects of STAT3 inhibitor S3I-201 on tumor cells, we analyzed the expression level of p-STAT3, survival maker survivin and proliferation marker Ki-67 in ASCC control and S3I-201 groups." (PMID 28747781, 2017). "Further, we evaluated the prognostic value of the combination of SHP2 and STAT3 in tumor samples from a cohort of CRC patients with known clinical history." (PMID 29242509, 2017). "miR-874-3p has been consistently shown in various tumour types to be a tumour suppressive miRNA through regulation of STAT3, CDK9 and E2F3 expression." (PMID 28076852, 2017). "When STAT3 was activated, MDSCs promoted tumor growth by suppressing T cells and expanding Cancer stem cells (CSCs) populations." (PMID 28747781, 2017). "Abnormal activation of STAT3 was reported to be involved in DC regulatory function under tumor conditioned medium." (PMID 28099147, 2017). "We observed that the protein levels of p-JAK, p-STAT3 and IL-8 in tumor specimens of curcumin combination with EGCG-treated group were decreased significantly, which corroborated our in vitro results." (PMID 28967875, 2017). "STAT3 activation induces IL-6 expression in both tumor and stromal cells and creates a tumor-promoting inflammatory microenvironment." (PMID 28725043, 2017). "Ectopic expression of ZAP-70 induced transcription of miR-21 via MAPK and STAT3, which subsequently induced downregulation of tumor suppressors targeted by miR-21." (PMID 28947822, 2017).